GINS1 (GINS complex subunit 1)
Diseases named in the same sentence as GINS1 in open-access papers (continued):
Sharing a sentence is not in itself a finding about the gene and the disease.
desmoid tumor (1 paper, 2025). A desmoid tumor (DT) is a benign, locally invasive soft tissue tumor associated with a high recurrence rate but with no metastatic potential. "Other trials substantiated that GINS1 might be a target of sorafenib which significantly prolonged the PSF and induced durable responses among patients with progressive, refractory, or symptomatic desmoid tumors." (PMID 40123906, 2025).
esophageal cancer (1 paper, 2025). A primary or metastatic malignant neoplasm involving the esophagus. "The results showed that COL4A1, DEK, GINS1, HPCAL1, KIF4A and RBMX were significantly increased in esophageal cancer tissues and decreased in the combined treatment group, suggesting that are potential prognostic markers." (PMID 41326355, 2025). "Decreased levels of COL4A1, DEK, GINS1, HPCAL1, KIF4A and RBMX predicted longer survival in esophageal cancer patients, while overexpression of IGFL1P1, LRRC57A-AS1, SNHG3, ULK3 and ZFYVE19 correlated with longer survival." (PMID 41326355, 2025).
fibrosarcoma (1 paper, 2022). A malignant mesenchymal fibroblastic neoplasm affecting the soft tissue and bone. "In fibrosarcoma, malignant fibrous histiocytoma and round cell liposarcoma, GINS1 was also more highly expressed than in normal samples, and the fold changes were 9.773, 10.455 and 6.478." (PMID 35896011, 2022).
gastric cancer (1 paper, 2024). A primary or metastatic malignant neoplasm involving the stomach. "The literature review presented aligns with our findings that DSCC1 and GINS1 are overexpressed in Gastric cancer, and higher expression levels are associated with poor prognosis." (PMID 38301047, 2024). "In summary, DSCC1 and GINS1 are overexpressed in gastric cancer, and higher expression levels are associated with worse prognosis." (PMID 38301047, 2024). "DSCC1 and GINS1 might be the complementary biomarkers of computed tomography for diagnostic grading of gastric cancer." (PMID 38301047, 2024). "The findings of this study reveal that DSCC1 and GINS1 are overexpressed in Gastric cancer, and higher expression levels are associated with worse patient outcomes, suggesting that these two genes may play pivotal roles in Gastric cancer." (PMID 38301047, 2024). "These heatmaps indicated higher expression of the core genes (DSCC1 and GINS1) in Gastric cancer samples compared to normal samples." (PMID 38301047, 2024). "Box plots of core gene expression in Gastric cancer and normal samples demonstrated differential expression of core genes (DSCC1 and GINS1), with higher expression in Gastric cancer samples and lower expression in normal samples." (PMID 38301047, 2024). "The RT-PCR results showed that, compared to the Control group, the mRNA expression levels of DSCC1 and GINS1 in the Gastric cancer group were significantly increased (P < 0.01)." (PMID 38301047, 2024). "DSCC1 and GINS1’s significant roles in gastric cancer will be validated using public datasets." (PMID 38301047, 2024). "WB and RT-PCR results demonstrated high expression of DSCC1 and GINS1 in gastric cancer." (PMID 38301047, 2024). "Consequently, DSCC1 and GINS1 are likely to play important roles in the development of Gastric cancer." (PMID 38301047, 2024). "However, complementary markers of computed tomography for diagnostic grading of gastric cancer are currently unclear, and the relationship between DSCC1 and GINS1 and gastric cancer remains unclear." (PMID 38301047, 2024). "In the Gastric cancer-OE group, the mRNA expression levels of DSCC1 and GINS1 were significantly higher than in the Gastric cancer group (P < 0.01)." (PMID 38301047, 2024). "In the Gastric cancer-KO group, the mRNA expression levels of DSCC1 and GINS1 were significantly lower than in the “Gastric cancer” group (P < 0.01)." (PMID 38301047, 2024). "A heatmap of core gene expression in Gastric cancer survival data indicated that the core genes, DSCC1 and GINS1, acted as protective factors." (PMID 38301047, 2024). "However, complementary markers for gastric cancer, relationship between DSCC1, GINS1 and gastric cancer remain unclear." (PMID 38301047, 2024). "However, the exact relationship between DSCC1, GINS1, and Gastric cancer is not yet clear." (PMID 38301047, 2024).
gastric tumors (1 paper, 2024). "The core genes (DSCC1 and GINS1) were found to be associated with gastric neoplasms, gastrointestinal diseases, tumors, gastritis, inflammation, and necrosis." (PMID 38301047, 2024). "CTD analysis revealed associations between DSCC1, GINS1 and gastric tumors, gastrointestinal diseases, tumors, gastritis, inflammation, necrosis." (PMID 38301047, 2024).
lentivirus infection (1 paper, 2023). Virus diseases caused by the Lentivirus genus. "Western blot results confirmed that GINS1 expression was depressed in SU-DHL2 cells and increased in FARAGE cells after lentivirus infection." (PMID 37576391, 2023).
leukemia (1 paper, 2023). A malignant (clonal) hematologic disorder, involving hematopoietic stem cells and characterized by the presence of primitive or atypical myeloid or lymphoid cells in the bone marrow and the blood. "GINS1 is overexpressed in several types of cancers including leukemia and linked to poor outcomes." (PMID 37576391, 2023). "In particular, upregulation of GINS1 has been reported in leukemia, non-small cell lung cancer, and breast cancer." (PMID 37576391, 2023). "GINS1 was highly expressed in several types of leukemias, and knockdown of GINS1 reduced the growth of AML and CML cells." (PMID 37576391, 2023). "High expression of GINS1 also promotes AraC resistance and cell cycle transit in leukemia cells." (PMID 37576391, 2023).
lung squamous cell carcinoma (1 paper, 2022). "The mRNA expression of BIRC5, SHCBP1, CCNA2, SKA3, and GINS1 in LUAD and lung squamous cell carcinoma (LUSC) tissues were all significantly higher than that in normal tissues." (PMID 34806315, 2022).
lymphopenia (1 paper, 2018). Reduction in the number of lymphocytes. "Interestingly, patients with deficiencies in Mcm4 and Gins1, which are involved in DNA helicase complexes, have a profound NK cell lymphopenia." (PMID 29868001, 2018).
pleomorphic liposarcoma (1 paper, 2022). Pleomorphic liposarcoma (PLS), the rarest subtype of liposarcoma (LS), is an aggressive, fast growing tumor located usually in the deep soft tissues of the lower and upper extremities. "In Detwiller Sarcoma dataset, the mRNA expression of GINS1 in pleomorphic liposarcoma was higher than in normal samples, with a fold change of 10.222." (PMID 35896011, 2022).
serous ovarian carcinoma (1 paper, 2012). "Interestingly, hsa-miR-18a, which possesses a significant positive correlation with GINS1 (along with NUSAP1) has shown to be highly up-regulated in serous ovarian carcinoma both previously and within our analysis." (PMID 22452920, 2012).
tumor (19 papers, 2012 to 2025). "Upregulated GINS1 was also associated with increased DC markers, which indicated a closed relationship between GINS1 and tumor DC penetration." (PMID 40123906, 2025). "The high expression of GINS1 was associated with several biological processes of tumor development including proliferation, invasion, and migration." (PMID 36451247, 2022). "We’ve described about that in mice experiment, knockdown of GINS1 expression caused inhibition of tumor growth." (PMID 35896011, 2022). "GINS1, a proliferative subtype (24%~34%), is endowed with elevated proliferative activity, high tumor purity, immune-desert, and PIK3CA mutations." (PMID 36345721, 2022). "Collectively, these results demonstrated that GINS1 was closely related to genetic alteration and methylation which could cause tumor proliferation and migration in LIHC." (PMID 40123906, 2025). "With high expression in stem cells and progenitor cells related to high proliferation potential, GINS1 promotes tumor growth." (PMID 40123906, 2025). "Analysis from the TIMER database unveiled that the expression of GINS1 in LIHC was correlated with several tumor-infiltrating immune cells including B cell, CD8+ T cell, CD4+ T cell, macrophage, neutrophil, and dendritic cell." (PMID 40123906, 2025). "Correlation between GINS1 expression and 6 types of tumor-infiltrating immune cells was analyzed using TIMER database." (PMID 40123906, 2025). "Results showed that the expression of GINS1 was correlated with tumor purity (r = 0.179), B cell (r = 0.479), CD8+ T cell (r = 0.335), CD4+ T cell (r = 0.344), macrophage (r = 0.46), neutrophil (r = 0.373), dendritic cell (r = 0.480) (all p < 0.05)." (PMID 40123906, 2025). "Further enrichment, methylation, and tumor immune microenvironment analyses showed an intimate connection with GINS1." (PMID 40123906, 2025). "As a well-established EMT regulator, ZEB1 was shown to be vitally implicated in GINS1-induced cancer progression through promoting EMT and tumor metastasis via β-catenin signaling." (PMID 38913193, 2024). "The results showed that GINS1 overexpression evidently increased tumor growth and tumor weight compared to the control group." (PMID 37576391, 2023). "In recent studies, GINS1 was reported to involve various processes of tumor genesis and development." (PMID 36451247, 2022). "In this regard, the knockout of GINS1 reportedly leads to cell cycle arrest in the G1/S phase, thereby reducing the proliferation of tumor cells." (PMID 36092720, 2022). "The transcriptional levels of GINS1/2/3/4 were significantly higher in SARC than in non-tumor tissues." (PMID 36092720, 2022). "GINS1 not only has the effect of anti-tumor but also can promote the antigen recognition process of cells." (PMID 36451247, 2022). "Immunohistochemistry of protein expression was further demonstrated that GINS1 was overexpressed in tumor tissues than normal tissues of 11 types of cancers, which played an important role in tumor development." (PMID 36451247, 2022). "In this study, we revealed that the expression of GINS1 was upregulated in most tumor tissues, and correlated with tumor malignancy on the whole." (PMID 36451247, 2022). "From the GSE68591 dataset, SARC samples exhibited significantly high transcriptional levels of GINS1/2/3/4 compared to non-tumor samples." (PMID 36092720, 2022). "Overwhelming evidence substantiates that up-regulation of GINS1 expression in HCC tumors is correlated with tumor grade." (PMID 36092720, 2022). "Subtypes with rich stromal components (e.g. GINS2 and GINS4) in human CRC samples were inclined to transform into subtypes with high tumor purity (e.g. GINS1 and GINS3) in corresponding PDX derivatives." (PMID 36345721, 2022). "Spheroid formation assay results showed that GINS1 promoted the stem cell activity of HCC tumor cells." (PMID 34414190, 2021).
tumor (continued). "In the present study, GINS1 was identified to be highly expressed in human HCC and associated with tumor grades and predicted poor patient survival." (PMID 34414190, 2021). "Here, we report that GINS1 was highly expressed in HCC tumors, associated with tumor grades, and predicted poor patient survival using Gene Expression Omnibus (GEO) databases exploration." (PMID 34414190, 2021). "Cell cycle, cell proliferation assay and in vivo xenograft mouse model indicated that knocking down GINS1 induced in G1/S phase cell cycle arrest and decreased tumor cells proliferation in vitro and in vivo." (PMID 34414190, 2021). "Knocking down GINS1 arrested cell cycle and decreased tumor cells proliferation in vitro and in vivo." (PMID 34414190, 2021). "In contrast, knockdown of GINS1 expression led to inhibited tumor growth by disrupting DNA replication and chromosomal segregation, and promoted apoptosis, particularly early apoptosis." (PMID 30100882, 2018). "Higher expression level of GINS1 was observed in breast and lung cancer cells, and was correlated to enhanced ability in tumor proliferation and poor patient survival." (PMID 30413605, 2018). "The mRNA and protein expression data of GINS1 were downloaded from The Cancer Genome Atlas (TCGA) database, the Clinical Proteomic Tumor Analysis Consortium (CPTAC), the University of Alabama at Birmingham CANcer Data Analysis Portal (UALCAN), and the Human Protein Atlas (HPA) database." (PMID 40123906, 2025). "However, upregulation of GINS1 rescued the tumor volumes and weights suppressed by FOXP1- silencing in the SU-DHL2-shFOXP1+oeGINS1 groups, indicating that GINS1 overexpression reversed the growth inhibition induced by FOXP1 knockdown." (PMID 37576391, 2023). "It reconfirmed that GINS1 high expressed in tumor and harm to survival time." (PMID 36451247, 2022). "Several recent studies have suggested that GINS1 plays an important role in tumor growth." (PMID 34806315, 2022). "GINS1 can affect tumor cell proliferation by regulating cell cycle checkpoints and DNA replication, so inhibiting GINS1 may be an effective strategy for tumor treatment." (PMID 36451247, 2022). "Moreover, GINS1 likely activated the RAS oncogenic pathway, promoted the stem cell activity of tumor cells, and caused sorafenib resistance." (PMID 34414190, 2021). "Furthermore, xenograft mouse model results showed that ablation of GINS1 inhibited tumor growth in vivo." (PMID 34414190, 2021). "Therefore, GINS1 was regarded as a key gene to promote tumor growth." (PMID 36451247, 2022). "GINS complex subunit 1 (GINS1) promotes EMT and tumor metastasis by favoring β-catenin signaling, while Forkhead box O3 (FOXO3a) reduces the binding of β-catenin to the T-cell factor (TCF) and inhibits β-catenin/TCF target gene expression." (PMID 41303618, 2025). "Then, mRNA levels of GINS1/2/3/4 in SARC and non-tumor tissues were detected in TCGA and GTEx databases." (PMID 36092720, 2022). "This is based on ample evidence that replication stress can induce CIN and our observation that replication factors are over-expressed in tumours with high levels of W-CIN and that over-expression of the replication genes GINS1 and CDC45 can induce W-CIN." (PMID 35326573, 2022). "Consistent with the ONCOMINE analysis, all four GINS genes were up-regulated in tumor samples of HCC from TCGA database with 6.382, 3.789, 2.442, and 2.770-fold elevation for GINS1, GINS2, GINS3, and GINS4 mRNA expressions, respectively (P<0.001 for all)." (PMID 30413605, 2018). "Apart from the immune activation represented by GINS5, GINS1/2/3 displayed sparse infiltration of cells that promote immune activity, but unlike GINS2, GINS1/3 were also characterized by rare immunosuppressive cells, consistent with their high tumor purity." (PMID 36345721, 2022).
tumor (continued). "We found that GINS1 expression was positive correlated with tumor purity (r = 0.338, p = 5.94e-08), and negative correlated with the levels of tumor-infiltrating CD4+ T cell (r = −0.234, p = 2.56e-04) and macrophages (r = −0.233, p = 3.21e-04)." (PMID 36092720, 2022). "Decreased survival was observed in Kaplan Meier survival curves for cases with MCM 2, 4, and 5, CDC45, GINS1, and MCM10 expression above the tumor cohort average, in agreement with the general concept that high expression of proliferation genes correlates with decreased survival." (PMID 31857847, 2019). "Furthermore, expression inhibition of TMPO, TOP2A, RFC3, GINS1, and CKS2 genes could prevent tumor growth." (PMID 34249670, 2021). "In addition, expression inhibition of TMPO, TOP2A, RFC3, GINS1, and CKS2 genes could prevent tumor growth and TRIB3 expression suppression would be a favorable target for anti−angiogenic therapy." (PMID 34249670, 2021).
cancer (17 papers, 2017 to 2025). A tumor composed of atypical neoplastic, often pleomorphic cells that invade other tissues. "Reportedly, dysregulation of GINS1 has been demonstrated in association with an ominous prognosis and the progression of cancers." (PMID 40123906, 2025). "Moreover, dysregulation of GINS1 has been demonstrated in association with a poor prognosis and the progression of malignant tumors." (PMID 40123906, 2025). "GINS1 is correlated with a poor prognosis in numerous cancers including liver hepatocellular carcinoma (LIHC)." (PMID 40123906, 2025). "In our previous research, it was revealed that aberrantly high GINS1 levels promoted cancer cell proliferation and indicated a poorer prognosis for patients with DLBCL21." (PMID 37576391, 2023). "The high expression of GINS1 was not only promoting the development of cancers but also affecting their prognosis." (PMID 36451247, 2022). "The overall survival (OS) showed that the high GINS1 expression group had a low survival rate in 11 types of cancer patients in general." (PMID 36451247, 2022). "Data of the GEO database revealed that HRAS oncogenic signature were enriched in Gins1 high-expressed cancer cells, and silencing GINS1 decreased RAS, SKP2 and LIF expression in our experiments." (PMID 34414190, 2021). "Another study showed that high expression of GINS1 in cancer cells promoted cell proliferation, transplantation, and metastatic properties." (PMID 31755218, 2020). "The results revealed that YB-1 knockout led to significant decreases in the promoter activities of the FZD-1, p21, GLP-1, GINS1, and Notch2 genes in cancer stem cells." (PMID 31375149, 2019). "The results of ChIP-seq showed that YB-1 maintained the stemness of cancer stem cells by promoting the expressions of stemness-associated genes (FZD-1, p21, GLP-1, GINS1, and Notch2)." (PMID 31375149, 2019). "Here, GINS1 was found aberrantly expressed in diverse cancers based on pan-cancer analysis." (PMID 40123906, 2025). "The oncogenic role of GINS1 in human cancers has been mentioned in many recent studies." (PMID 40123906, 2025). "Dysfunctional GINS1 may lead to DNA replication errors, chromosome instability, and cell cycle issues, highly relevant to various diseases, including cancer." (PMID 38301047, 2024). "Notably, a significantly higher expression of GINS1 in cancer tissues was observed than in normal tissues." (PMID 36451247, 2022). "Therefore, the connection between GINS1 expression and COVID-19 infection in cancers needs experimental evidence." (PMID 36451247, 2022). "Then, we investigated the GINS1 survival rate in cancers by GEPIA." (PMID 36451247, 2022). "Indeed, ectopic expression of miR‐101‐5p and knockdown of GINS1 significantly blocked cancer cell aggressive phenotypes in MDA‐MB‐157 cells." (PMID 31755218, 2020). "As reported, the GINS1 protein is a DNA replication modulation factor that is widely expressed in stem cells to regulate proliferation and migration and is closely related to the occurrence and proliferation of cancer cells." (PMID 31375149, 2019). "In this context, the transcription factor YB-1 could promote cancer stem cell proliferation, maintain cancer stem cell stemness, and suppress cancer stem cell apoptosis by promoting the expression of GINS1, p21, GLP-1, Notch2, and FZD-1." (PMID 31375149, 2019). "However, rescue of YB-1 expression resulted in significant increases in the promoter activities of the FZD-1, p21, GLP-1, GINS1, and Notch2 genes in YB-1 knockout cancer stem cells." (PMID 31375149, 2019). "Furthermore, GEO database (GSE17112) analysis showed that HRAS oncogenic gene set was enriched in GINS1 high-expressed cancer cells, and quantitative real-time PCR, and Western blot results proved that GINS1 enhanced HCC progression through regulating HRAS signaling pathway." (PMID 34414190, 2021).